ERVFRD-3 (endogenous retrovirus group FRD member 3)
Gene: Transcribed processed pseudogene on chromosome 9 (21,929,457 to 21,931,073, forward strand). Ensembl gene ENSG00000264801.
Diseases named in the same sentence as ERVFRD-3 in open-access papers:
ERVFRD-3 is named in the same sentence as 2 diseases in open-access papers, as found by Europe PMC text mining. Sharing a sentence is not in itself a finding about the gene and the disease. The quoted sentences say what the papers report.
melanoma (1 paper, 2024). A malignant, usually aggressive tumor composed of atypical, neoplastic melanocytes. "For example, of the 16 total genes driving the association between melanoma and nevus count, only two (MTAP and ERVFRD‐3) were shared by all three tissues, and six (MAFF, HEBP1, HTR7P1, EMP1, GPRC5A, C9orf66) were specific to melanocyte." (PMID 38308491, 2024).
ERVFRD-3 also shares sentences with these, for which no sentence is quoted: nevus (1 paper).